BMP2 (bone morphogenetic protein 2)
Diseases named in the same sentence as BMP2 in open-access papers (continued):
Sharing a sentence is not in itself a finding about the gene and the disease.
ankylosing spondylitis (5 papers, 2013 to 2023). An autoimmune chronic inflammatory disorder characterized by inflammation in the vertebral joints of the spine and sacroiliac joints. "Three independent studies have demonstrated that BMP-2 serum concentration was in the range of 100 pg/mL and neatly higher in ankylosing spondylitis patients than in healthy controls." (PMID 33046134, 2020).
cleft lip (5 papers, 2014 to 2025). Congenital defect in the upper lip where the maxillary prominence fails to merge with the merged medial nasal prominences. "This systematic review aims to assess the efficacy of recombinant human bone morphogenetic protein-2 (rhBMP-2) as a treatment modality for children with cleft lip and palate compared to the conventional iliac crest bone grafting approach." (PMID 40003593, 2025). "Autologous bone and rh-BMP2 graft showed a similar effectiveness in maxillary alveolar reconstruction in patients with unilateral cleft lip and palate assessing bone graft volume and height although rh-BMP2 graft showed a relative shorter length of hospital stay (high uncertainty level)." (PMID 30740615, 2019). "A recent study also suggested that gene BMP2 is strongly associated with cleft lips and that cases of absent teeth are directly related to the severity of the cleft found in the patient." (PMID 25215247, 2014). "Eight significant variants associated with craniofacial malformations such as non-syndromic cleft lip and palate, mandibular prognathism, ocular abnormalities, and tooth defects are found in AXIN2, BMP2, BMP4, NOTCH3, PTCH1, SOX10, and WNT10A." (PMID 38785976, 2024). "Maxillary alveolar reconstruction in four patients presenting a unilateral cleft lip and palate with or without autologous bone graft with rh-BMP-2 graft showed similar results regarding bone graft volume and height, although the hospitalization length was reduced." (PMID 38137899, 2023).
colitis (5 papers, 2021 to 2025). Inflammation of the colon. "Here, the authors show that IFN-γ, produced by immune cells in response to chemically induced colitis, acts as a central driver of crypt reorganization by inducing apoptosis and extrusion of BMP2-expressing colonocytes." (PMID 40319019, 2025). "In our study, the expression of the BMP2 gene was upregulated, which was consistent with a study conducted in a murine colitis model where TNBS was used as an inducer." (PMID 36500396, 2022). "BMP4 expression was similar in the early and late stages of colitis, whereas BMP2 expression was considerably higher in the acute stage." (PMID 36500396, 2022). "Taken together, these findings suggest that BMP2 plays a role in the pathogenesis of TNBS colitis, but the exact mechanism remains unclear." (PMID 37391444, 2023). "In contrast, during acute colitis, Bmp2 expression was strongly reduced in WT but not in IFN-γR KO mice, as was the BMP target gene Id1 (b right)." (PMID 40319019, 2025). "BMP2 is expressed in the mature colonocytes of the epithelial surface of the normal colon and it influences the same cells that produce in an autocrine manner, but its expression increases significantly during the acute phase of 2,4,6-trinitrobenzene sulfonic acid (TNBS)-induced colitis." (PMID 37391444, 2023).
fibrosis (5 papers, 2022 to 2026). the formation of excess fibrous connective tissue in an organ or tissue in a reparative or reactive process. "However, genes associated with cartilage fibrosis (such as Sparc and Col1a1) and hypertrophy (e.g., Ibsp, Bmp2, Mmp13, and Matn4) presented the highest expression levels at 6 weeks." (PMID 40722047, 2025). "Transient decreased expression of BMP2 after partial hepatectomy was found during the process of liver regeneration in rats, while upregulation of BMP2 was observed during carbon tetrachloride (CCl4)-induced fibrosis in rats, in mice after chronic alcohol exposure, and in NAFLD patients." (PMID 38468450, 2024).
hemochromatosis (5 papers, 2013 to 2025). A disorder of iron metabolism characterized by a triad of HEMOSIDEROSIS; LIVER CIRRHOSIS; and DIABETES MELLITUS. "Most hemochromatosis genetic base conditions are linked to BMP2 as a result of homozygosity for the C282Y missense mutations that cause modification in the HFE gene." (PMID 34780475, 2021). "Although not yet implicated in erythropoiesis, a significant association was demonstrated between rs235756 in BMP2 and ferritin levels in a study of genetic modifiers of hemochromatosis." (PMID 24058921, 2013). "BMP2 570 A>T polymorphism was associated with iron overload in hemochromatosis patients." (PMID 41157574, 2025). "Variants in bone morphogenic protein (BMP)-2 may also modify the phenotype of HFE C282Y hemochromatosis and lead to high iron burden." (PMID 37179448, 2023). "Variants of the BMP2 gene have previously been associated with hemochromatosis but not with IDA." (PMID 34780475, 2021). "Variants of BMP2 have previously been associated with hemochromatosis, but not IDA." (PMID 34780475, 2021).
hyperphosphatemia (5 papers, 2022 to 2025). Abnormally high level of phosphate in the blood. "Hyperphosphatemia activates multiple signaling pathways, including NF-κB, Wnt/β-catenin, and BMP-2/Smad, inducing osteogenic phenotypic transformation of vascular smooth muscle cells (VSMCs)." (PMID 41166265, 2025). "In this review, we have discussed the regulatory roles of hyperphosphatemia, BMP2 and RUNX2 in the progression of vascular calcification." (PMID 39308809, 2024). "In response to hyperphosphatemia, inflammation, and oxidative stress, VSMCs lose their contractile phenotype and adopt osteoblast-like features, driven by transcription factors such as Runx2, BMP2, and Msx2." (PMID 41470171, 2025). "In summary, hyperphosphatemia can be seen as the initiating factor in a series of regulatory mechanisms during the VC process secondary to CKD, mediating the expression of BMP2 and RUNX2, which are crucial molecules affecting the VC process." (PMID 39308809, 2024). "Hyperphosphatemia was identified to convert the contractile phenotype of vascular smooth muscle cells to the osteogenic phenotype, during which DNA 6 mA demethylated by ALKBH1 facilitated OCT4 to recognize and bind to BMP2 promoter." (PMID 36581839, 2022).
Insulin resistance (5 papers, 2017 to 2025). Increased resistance towards insulin, that is, diminished effectiveness of insulin in reducing blood glucose levels. "BMP4, which is closely related to BMP2 was recently found to be upregulated in the serum of two diabetic mouse models and was proposed to contribute to insulin resistance by inhibiting IRS-1 activation and insulin signaling." (PMID 29222456, 2017). "Collectively, these findings suggest the BMP2 and BMP6 pathway(s) as promising new drug targets to treat insulin resistance." (PMID 29222456, 2017).
leukemia (5 papers, 2015 to 2022). A malignant (clonal) hematologic disorder, involving hematopoietic stem cells and characterized by the presence of primitive or atypical myeloid or lymphoid cells in the bone marrow and the blood. "Careful analysis of leukemia cell EV content and phenotypic outcomes provide evidence that vesicles are implicated in transferring several known key mediators of chemoresistance, including miR-155, IL-8, and BMP-2." (PMID 32117744, 2020). "Alteration of BMP receptor type 1b (BMPR1b) expression at the HSC surface is induced by the expression of BCR-ABL and these molecular changes led to altered responses of leukemia cells to BMP2 and BMP4 as compared to normal bone marrow cells." (PMID 35047500, 2021). "The notion of BMP2 specifically as a responsible TERS factor in the AML BM is consistent with its known role in leukemia progression and induction of osteogenic differentiation, respectively." (PMID 31289607, 2019). "In contrast to that TGF-β1 level in AML patients was much lower than that of healthy donors, we found that the concentration of BMP2 was abnormally upregulated, which was positively correlated with the frequency of leukemia blasts and the emergence of Reg-Vδ2 cells in the bone marrows of AML." (PMID 36325350, 2022). "Other studies have reported that the anti-proliferative effect of BMP-2 in different tumor cell lines, including gastric, colon, and leukemia, may involve induction of apoptosis." (PMID 25797254, 2015).
Peri-Implantitis (5 papers, 2020 to 2024). An inflammatory process with loss of supporting bone in the tissues surrounding functioning DENTAL IMPLANTS. "The use of HMME@ZIF-8/Met/BMP-2@PLGA/GelMA composite hydrogels in combination with ultrasound can provide a novel option for treating peri-implantitis in the future." (PMID 38854857, 2024). "In this study, we tested an immediate peri-implantitis model and a conventional peri-implantitis model when a potent bone-inducing morphogene, BMP-2, was applied with a method of ex vivo gene delivery using PDLSCs." (PMID 32108172, 2020). "In this study, we aimed to compare the regenerative outcomes between both models when ex vivo BMP2 gene therapy using autologous periodontal ligament stem cells (B2/PDLSCs) was applied to peri-implantitis defects." (PMID 32108172, 2020). "Ex vivo BMP2 gene delivered BMSCs were applied into rat critical-sized calvarial defects, whereas B2/PDLSC were transplanted into the canine peri-implantitis model." (PMID 32108172, 2020).
pulmonary fibrosis (5 papers, 2021 to 2025). Chronic progressive interstitial lung disorder characterized by the replacement of the lung tissue by connective tissue, leading to progressive dyspnea, respiratory failure, or right heart failure. "Continuous activation of TGFβ and repression of BMP2-driven signaling can lead to the progression and aggravation of lung fibrosis." (PMID 38673961, 2024). "In bleomycin-induced pulmonary fibrosis, pathways elicited by TGFβ and BMP2 follow an inverse course." (PMID 38673961, 2024). "Knockdown of miR-218 in MSCs partially abrogated the beneficial effects of MSC-Exos, while transfection of miR-218 and its overexpression in MSC-Exos resulted in increased BMP2 expression, which led to the attenuation of EndMT and alleviation of pulmonary fibrosis." (PMID 38673961, 2024). "Zhang and colleagues showed that MSC-Exos increased Wnt5a/BMP2-driven signaling and suppressed Wnt/β-catenin-dependent collagen deposition and EMT in inflamed and fibrotic lungs, which resulted in the attenuation of pulmonary fibrosis." (PMID 38673961, 2024).
renal carcinoma (5 papers, 2013 to 2021). A carcinoma arising from the epithelium of the renal parenchyma or the renal pelvis. "Here, we summarize potential targeting strategies for renal cancer cells and renal CSCs, including tyrosine kinase inhibitors, mammalian target of rapamycin inhibitors (mTOR), interleukins, CSC marker inhibitors, bone morphogenetic protein-2, antibody drug conjugates, and nanomedicine." (PMID 27891093, 2016).
aortic valve calcification (4 papers, 2016 to 2022). "DCBLD2 expression is decreased in human CAVD, and a combination of genetic background, i.e., DCBLD2 deficiency, and BAV promotes aortic valve calcification and stenosis through enhanced BMP2 signaling in Dcbld2−/− mice." (PMID 35540096, 2022). "Previous studies have shown BMP2 as an important proosteogenic factor involved in vascular and aortic valve calcification." (PMID 36246570, 2022). "Combined, these findings indicate that in the context of the same genetic background, the presence of BAV promotes aortic valve calcification and stenosis through enhanced BMP2 signaling." (PMID 35540096, 2022). "However, existing evidence indicates that BMP2 is insufficient by itself and additional factors are required to induce aortic valve calcification." (PMID 35540096, 2022). "Therefore, the osteogenic effect of BMP2 on AVICs may play an important role in aortic valve calcification and CAVD progression." (PMID 36246570, 2022). "In addition to TGF-β1, elevated levels of Bone morphogenetic protein 2 (BMP-2) and BMP-4 expression, two pro-osteogenic cytokines belonging to the TGF-β superfamily, have been observed in stenotic calcific aortic valve disease (CAVD) leaflets." (PMID 27420053, 2016).
coronary artery disease (4 papers, 2015 to 2025). "Considering BMP2 reports, some studies have associated increased serum levels of this BMP with coronary artery disease in diabetic patients." (PMID 35614516, 2022). "According to a recent study reveals elevated IL-29 expression in calcified carotid arteries of patients with coronary artery disease or CKD, where it positively correlates with bone morphogenetic protein 2 (BMP2) level." (PMID 40959491, 2025).
dental caries (4 papers, 2023 to 2025). The decay of a tooth, in which it becomes softened, discolored, and/or porous. "Forth, genetic confounding between short stature and dental caries may exist, considering that GHR and BMP2 are associated with enamel dysplasia in the permanent teeth." (PMID 38248567, 2024).
glaucoma (4 papers, 2009 to 2025). Increased pressure in the eyeball due to obstruction of the outflow of aqueous humor. "BMP-2 is involved in the scleral remodeling process, and BMP-4 is associated with the onset and treatment of glaucoma and strabismus." (PMID 40696418, 2025). "Among the genes that were downregulated with the polyherbal and were related to the development of glaucoma are BMP2 and IL3, identified by bioinformatics analysis." (PMID 35625159, 2022). "On the other hand, BMP2 have been shown to increase ECM deposition, and BMP2 activity in HTM cells has been proposed to contribute to outflow resistance by the induction of osteogenic factors during aging and glaucoma." (PMID 19279691, 2009).
heart failure (4 papers, 2018 to 2024). Inability of the heart to pump blood at an adequate rate to meet tissue metabolic requirements. "In the heart failure mice, qPCR showed no significant change in Bmp2, Bmp4, Nkx2.5, Shox2 and Tbx3 in the sinus node, but there was a significant downregulation of Tbx18 and Isl1 and upregulation of AP1, Mef2c and NRSF mRNA." (PMID 32647133, 2020).
infertile (4 papers, 2015 to 2021). "This KLF-BMP appears important as the endometrial stromal cells of bmp2-deleted mice are infertile." (PMID 31256208, 2019).
iron deficiency (4 papers, 2014 to 2024). "The BMP2 mRNA level was reduced during the whole experiment, suggesting that activin and BMP2 reacted differently to iron deficiency." (PMID 37175630, 2023). "The purpose of the current study is to investigate TMPRSS6 rs1421312 and BMP2 rs235756 SNPs and their association with iron deficiency status among female students at the University of Tabuk, Saudi Arabia." (PMID 34780475, 2021). "As far as we know, this is first article reporting on the association of polymorphism rs235756 of the BMP2 gene with iron deficiency status." (PMID 34780475, 2021). "The mRNA expression of the endometrium receptivity-related genes, PR, SOX-17, CX3CR1, FKN, activin, follistatin, BMP2, as well as the examined cytokines and chemokines LIF, IL-6, and IL-1β, were significantly downregulated at DFO-induced iron deficiency in HEC-1A cells." (PMID 37175630, 2023). "Based on these observations, it is supposed that FKN provides a positive effect on activin mRNA expression as well as on BMP2 and FKN secretions that may support endometrium receptivity at iron deficiency." (PMID 37175630, 2023).
iron overload (4 papers, 2021 to 2025). "So, this specific polymorphism of BMP2 may result in defective BMP2 secretion and/or addressing, compromising the SMAD signaling pathway and hepcidin gene expression, increasing the risk of iron overload and fibrosis." (PMID 41157574, 2025).
Lewis lung carcinoma (4 papers, 2020 to 2022). "Altogether, BMP2 signaling was observed to enhance bone metastases of Lewis lung carcinoma via PNMA5 in vivo." (PMID 34136487, 2021). "After that, we injected the vehicle or 20 ng/mL BMP2 pre‐treated LLCs into the left hind legs of C57BL/6 mice subcutaneously to analyse the direct invasion of Lewis lung carcinoma in the hind legs." (PMID 32750747, 2020). "We also found that α‐Sma+ marked fibroblasts expressed more BMP2 than other cell types in bone metastases of Lewis lung carcinoma." (PMID 32750747, 2020). "BMP2 originated from stroma fibroblasts contributed to the migration and invasion of Lewis lung carcinoma cells." (PMID 32750747, 2020). "Activation of BMP2 signaling can enhance BM of Lewis lung carcinoma." (PMID 34722241, 2021). "Although the difference was not statistically significant in numbers which could be attribute to the small number of mice investigated, BMP2 still had the trend to enhance the migration and invasion of Lewis lung carcinoma cells in vivo." (PMID 32750747, 2020). "Although BMP2 was a well‐known protein with bone inductivity, how BMP2 in combination with NSCLC cells to regulate the osteoblastic mechanism in bone metastases of Lewis lung carcinoma was largely unknown." (PMID 32750747, 2020). "BMP2 signalling activation can enhance bone metastasis of Lewis lung carcinoma." (PMID 32750747, 2020). "Besides, BMP2 plays role in both osteolytic mechanism and osteoblastic mechanism of Lewis lung carcinoma bone metastasis." (PMID 32750747, 2020). "And BMP2 could enhance the migration and invasion of Lewis lung carcinoma in vivo." (PMID 32750747, 2020).